LCE1A (late cornified envelope 1A)
Description:
Precursors of the cornified envelope of the stratum corneum.
Synonyms: LEP1
Tractability: No criterion of Open Targets' tractability assessment is met for any kind of drug.
Gene: Protein-coding gene on chromosome 1 (152,827,473 to 152,828,097, forward strand). Ensembl gene ENSG00000186844.
Pathways (Reactome):
Developmental Biology: Formation of the cornified envelope
Gene Ontology:
Molecular function: protein binding
Biological process: epidermis development
Cellular component: cytosol
Genetic constraint (gnomAD): Loss-of-function variants: 4 observed, 7.17 expected, observed/expected ratio (o/e) 0.56, 90% interval 0.27 to 1.27. That is too few expected variants to judge how well the gene tolerates losing a copy. Missense variants: 138 observed, 137.39 expected, observed/expected ratio (o/e) 1, 90% interval 0.87 to 1.16. Synonymous variants: 59 observed, 49.82 expected, observed/expected ratio (o/e) 1.18, 90% interval 0.96 to 1.47.
Homologues: Orthologues: chimpanzee LCE1A (97% identical).
Diseases named in the same sentence as LCE1A in open-access papers:
LCE1A is named in the same sentence as 1 disease in open-access papers, as found by Europe PMC text mining. Sharing a sentence is not in itself a finding about the gene and the disease.
LCE1A shares sentences with these, for which no sentence is quoted: Epileptic encephalopathy (1 paper).